STC2 (stanniocalcin 2)
Description:
Has an anti-hypocalcemic action on calcium and phosphate homeostasis.
Synonyms: STC-2; STCRP
Tractability: Antibody: UniProt places it where antibodies can reach, with high confidence; UniProt predicts a signal peptide or a membrane-spanning region; its Gene Ontology location is reachable by antibodies, with medium confidence. PROTAC: ubiquitination databases record sites on it.
Gene: Protein-coding gene on chromosome 5 (173,314,723 to 173,328,447, reverse strand). Ensembl gene ENSG00000113739.
Subcellular location: Secreted
Subcellular location (Human Protein Atlas): Endoplasmic reticulum; Predicted to be secreted
Pathways (Reactome):
Metabolism of proteins: Post-translational protein phosphorylation; Regulation of Insulin-like Growth Factor (IGF) transport and uptake by Insulin-like Growth Factor Binding Proteins (IGFBPs)
Gene Ontology:
Molecular function: enzyme binding; heme binding; protein homodimerization activity; hormone activity
Biological process: negative regulation of gene expression; regulation of hormone biosynthetic process; intracellular calcium ion homeostasis; cellular response to hypoxia; decidualization; embryo implantation; response to peptide hormone; response to vitamin D; signal transduction
Cellular component: endoplasmic reticulum; extracellular region; perinuclear region of cytoplasm; endoplasmic reticulum lumen; Golgi apparatus
Genetic constraint (gnomAD): Loss-of-function variants: 10 observed, 22.34 expected, observed/expected ratio (o/e) 0.45, 90% interval 0.28 to 0.76. The upper end of that interval is the gene's LOEUF score, 0.76, which puts it in group 3 of 6, group 1 being the genes least tolerant of losing a copy. Missense variants: 336 observed, 399.31 expected, observed/expected ratio (o/e) 0.84, 90% interval 0.77 to 0.92. Synonymous variants: 158 observed, 162.11 expected, observed/expected ratio (o/e) 0.97, 90% interval 0.86 to 1.11.
Homologues: Orthologues: chimpanzee STC2 (99% identical), macaque STC2 (99% identical), pig STC2 (92% identical), dog STC2 (91% identical), guinea pig STC2 (89% identical), rabbit STC2 (89% identical), mouse Stc2 (86% identical), rat Stc2 (84% identical), tropical clawed frog stc2 (66% identical), zebrafish stc2a (53% identical), zebrafish stc2b (46% identical), Caenorhabditis elegans W01A8.8 (12% identical). Paralogues in human: STC1 (25% identical).
Diseases named in the same sentence as STC2 in open-access papers:
STC2 is named in the same sentence as 132 diseases in open-access papers, as found by Europe PMC text mining. Sharing a sentence is not in itself a finding about the gene and the disease. The quoted sentences say what the papers report.
breast carcinoma (50 papers, 2014 to 2026). "Decreased expression of the STC2 gene, which has an anti-hypocalcemic effect on calcium and phosphate homeostasis, is associated with a poor prognosis in breast cancer." (PMID 41226241, 2025). "This analysis showed a significant enrichment of gene sets related to ER regulation and associated pathways, indicating a strong link between STC2 and ER-driven breast cancer." (PMID 40006048, 2025). "We found five proteins associated with the risk of breast cancer, such as STC2 and CRLF1 [1.33 (1.23–1.44) and 1.31 (1.21–1.42)]." (PMID 38750076, 2024). "Elevated STC2 levels are associated with tumour size, invasiveness, metastasis and poor prognosis in most tumours other than some breast cancers." (PMID 35501821, 2022). "STC2 expression was found to be higher in breast cancer patients with a predisposition toward late recurrence than in those with early metastases and relapses." (PMID 34612765, 2021). "STC2 was found to be implicated in breast cancer and gynecologic cancers, suggesting hormone-specific or -dependent activities in these malignancies." (PMID 34612765, 2021). "In agreement with the poorer outcome associated with low STC2 expression presented in this study, prior reports have shown that reduced stanniocalcin 2 expression promotes breast cancer cell proliferation, migration and invasion." (PMID 27556857, 2016). "Importantly, we found that STC2 was associated with multiple cancers including liver cancer, colon cancer, breast cancer, skin cancer and so on." (PMID 36685853, 2022). "STC2 expression was also associated with positive outcome in male breast cancer." (PMID 32296395, 2020). "STC2 is associated with a reduction in the viability of human breast cancer cells." (PMID 26951623, 2016). "High expression of STC2 mRNA was associated with good outcome in certain breast cancer patients." (PMID 25830567, 2015). "In this study, we investigated whether the expression of STC2 is associated with migration and invasion of breast cancer cells." (PMID 25830567, 2015). "Interestingly, STC2 overexpression in breast cancer is strongly associated with genetic alterations, such as amplifications and gains, which could explain its overexpression." (PMID 40006048, 2025). "Moreover, elevated STC2 is associated with poor outcomes in pancreatic, nasopharyngeal, ovarian, colon, and lung cancers, suggesting its role as a prognostic marker although, its role in breast cancer is controversial." (PMID 39186548, 2024). "In breast cancer, STC2 expression is positively correlated with ER status, suggesting potential relevance to ER-positive subtypes." (PMID 41596432, 2026). "Collectively, these findings underscore the potential of HIF-1α, CD44, and STC2 as both biomarkers and therapeutic targets in the management of breast cancer bone metastasis." (PMID 41596432, 2026). "This study aimed to assess the potential of STC2 as a predictive biomarker of response to chemotherapy in breast cancer." (PMID 40006048, 2025). "The identification of STC2 as a potential biomarker for predicting chemotherapy response has significant implications for breast cancer treatment." (PMID 40006048, 2025). "Existing studies have demonstrated that Stanniocalcin-2 (STC2) can regulate the protein kinase C/CLDN1 pathway to inhibit breast cancer invasion and metastasis." (PMID 40687428, 2025). "The results suggest that STC2 is significantly overexpressed in breast cancer, especially in the luminal A subtype." (PMID 40006048, 2025). "To further explore the expression patterns of STC2 across different molecular subtypes of breast cancer, we analyzed its expression using the Gene Expression Profiling Interactive Analysis 2.0 (GEPIA2.0) platform." (PMID 40006048, 2025). "In breast cancer specifically, STC2 is frequently co-expressed with the estrogen receptor (ER), a key driver of tumor growth expressed in about 80% of breast cancer cases." (PMID 40006048, 2025).
breast carcinoma (continued). "Increased STC2 levels are strongly correlated with tumour development, progression and poor prognosis for most human tumours except breast cancer." (PMID 39107307, 2024). "STC2 has been reported to be differently expressed and play vital functions in many other cancers, for example breast cancer with a classic cellular location in erinuclear region." (PMID 36803385, 2023). "For ruling out the possibility of IHC technical elements, we conducted the IHC experiment with same reagent and equipment in breast cancer samples, and the result showed that STC2 stains as expected in perinuclear region in these samples." (PMID 36803385, 2023). "In order to study the specific function of STC2 in breast cancer, we studied the expression profiles of STC2 in 54 breast cancer tissues by using qRT-PCR." (PMID 35513366, 2022). "The change in the STC2 expression plays a potential role in the carcinogenesis of breast cancer and ovarian cancer." (PMID 35102149, 2022). "cDNA microarray revealed a threefold induction of STC2 mRNA upon estrogen treatment in breast cancer cells." (PMID 35501821, 2022). "Clinically, STC2 mRNA and protein levels are positively correlated with Er expression in human breast cancer specimens." (PMID 35501821, 2022). "Results revealed that the expression level of STC2 in breast cancer tissues was distinctly higher compared to the precancerous lesions." (PMID 35513366, 2022). "In conclusion, STC2 had a significant inhibitory effect on the clonal formation of the two types of breast cancer cells." (PMID 35607324, 2022). "Our results confirmed that suppressing the expression of either STC2 or lncRNA MAFG-AS1 had the same impact on breast cancer proliferation and metastasis that were dramatically reduced." (PMID 35513366, 2022). "miR-190 regulates epithelial-mesenchymal transition (EMT) and angiogenesis through altering the activity of Erk and Akt signaling in an STC2-dependent manner in breast cancer cells." (PMID 35501821, 2022). "GEPIA 2 analysis indicates insignificant increase of STC2 expression in breast cancer comparing with their normal counterparts, showing inconsistence with the published wet-bench studies, which directly compared the expression of STC2 proteins in this tumour." (PMID 35501821, 2022). "Studies have showed that the expression of STC2 is broadly increased in human tumors including renal cell carcinoma, breast cancer, and colorectal cancer." (PMID 36685853, 2022). "The results showed that STC2 induced apoptosis in both breast cancer cell types in a dose-dependent manner." (PMID 35607324, 2022). "In conclusion, these results showed that LncRNA MAFG-AS1 regulated the expression of STC2 in breast cancer by promoting the stability of STC2 mRNA." (PMID 35513366, 2022). "We utilized CCK-8 and colony formation assays to dissect the knockdown of STC2 and found to be suppressed the breast cancer proliferation dramatically." (PMID 35513366, 2022). "The results showed that STC2 significantly inhibited the activity of the three kinds of breast cancer cells, with IC50 values below 5 μM, indicating significant antitumour activity." (PMID 35607324, 2022). "We detected STC2 expression in four different breast cancer tissues and normal breast cell lines, whose results showed that the expression level of STC2 in 4 breast cancer tissues was overtly higher compared to MCF-10A." (PMID 35513366, 2022). "Until now, the effects of STC2 on breast cancer have been studied widely, but research findings demonstrated two different views, one view is that STC2 plays an oncogenic role and the other is the opposite." (PMID 37287492, 2021). "DiMattia’s laboratory identified that estrogen, progesterone, and retinoic acid receptors played critical role in the regulation of STC2 in human breast carcinoma cell lines T-47D and MCF7." (PMID 34612765, 2021).
breast carcinoma (continued). "When a study was done to identifying estrogen-regulating genes in breast cancer lines in 2000, STC2 was first discovered to have relation with breast cancer." (PMID 37287492, 2021). "Several studies sought to explain the results by investigating the cellular mechanisms and relevant signaling pathways by which STC2 functioned in breast cancer." (PMID 34612765, 2021). "In this paper, it will summarize and evaluate the research data and results about mammalian STC2 on breast cancer." (PMID 37287492, 2021). "In human breast cancer, STC2 and estrogen receptor alpha were co-expressed, suggesting that STC2 exerted a positive prognostic role in estrogen receptor-associated breast cancer." (PMID 34612765, 2021). "The prognostic prediction significance of STC2 has been confirmed in gastric cancer, breast cancer, colorectal cancer and ovarian cancer." (PMID 32579175, 2020). "Taken together, except in breast cancer, STC2 expression is a potential prognostic marker for variety of cancers which promotes tumor cell growth, invasion and migration." (PMID 32296395, 2020). "Several reports suggest elevated expression of STC2 in human hepatocellular carcinoma, neuroblastoma, breast cancer, colorectal cancer, renal cell carcinoma, esophageal squamous cell cancer, and prostate cancer." (PMID 32296395, 2020). "The expression of STC2 is closely related to the prognosis of tumor patients, and its high expression leads to poor prognosis in patients with breast cancer, nasopharyngeal carcinoma, colorectal cancer, and renal cell carcinoma." (PMID 32411183, 2020). "In some breast cancer cells, STC2 inhibited migration and invasion via inhibition of protein kinase C (PKC) signaling." (PMID 32258098, 2019). "Evaluation of this gene set in the Molecular Taxonomy of Breast Cancer International Consortium (METABRIC) cohort of 1,964 patients identifies the F12 and STC2 genes as independent prognostic factors for overall survival in breast cancer." (PMID 27556857, 2016). "Stanniocalcin 2 expression is regulated by hormone signalling and an increase in stanniocalcin 2 expression levels leads to a reduction in breast cancer cell viability in vitro." (PMID 27556857, 2016). "Overexpression of stanniocalcin 2 also suppressed breast cancer cell migration and inhibited tumorigenesis and metastasis in a xenograft model of breast cancer." (PMID 27556857, 2016). "We found that breast cancer cell line 231 HM transfected with STC2 shRNA displayed high motility, fibroblast morphology, and enhanced cell migration and invasion." (PMID 25830567, 2015). "These authors showed that Stanniocalcin 2 (STC2) promoted breast cancer metastasis in mice through its interaction with claudin 1, which directly led to an alteration of the expression of the EMT molecules including Zeb1, Slug, and Twist." (PMID 26633531, 2015). "Gene profiling studies showed that STC2 was significantly elevated in a specific subset of breast cancer." (PMID 25830567, 2015). "To extend the function of STC2 in breast cancer, we investigated the influence of STC2 expression on apoptosis in breast cancer cells by use of Annexin V fluorescence apoptosis assay." (PMID 25830567, 2015). "To investigate the role of STC2 in migration and invasion of breast cancer cells, we performed migration assays using a high throughput screening multi-well insert 24-well two-chamber plates." (PMID 25830567, 2015). "Another common gene identified in both endometriosis and breast cancer in this study was stanniocalcin 2 (STC2)." (PMID 26512648, 2015). "For example, the secreted proteins conjugative transfer region 1 and stanniocalcin 2 serve as potential prognostic markers in breast cancer." (PMID 24932247, 2014). "It has been reported that STC2 expression was upregulated in various tumors, including breast cancer, prostate cancer, esophageal squamous cell carcinoma (ESC), gastric cancer, colorectal cancer, renal cell carcinoma (RCC) and neuroblastoma." (PMID 24606961, 2014).
breast carcinoma (continued). "Understanding these mechanisms could provide insights into how STC2 inhibitors might be developed and integrated into breast cancer treatment regimens." (PMID 40006048, 2025). "Recent studies have highlighted STC2 as a gene of interest in cancer biology due to its upregulation in a wide range of human cancers, including breast cancer, esophageal squamous-cell carcinoma, hepatocellular carcinoma, colorectal cancer, gastric cancer, renal cell carcinoma, and prostate cancer." (PMID 40006048, 2025). "The context-dependent role of STC2 in breast cancer could explain its differential predictive value for chemotherapy response." (PMID 40006048, 2025). "The results shown here provide evidence that STC2 gene expression could serve as a predictive biomarker for chemotherapy response in breast cancer patients." (PMID 40006048, 2025). "Since STC2 is associated with ER signaling pathway as well as previous studies identifying STC2 as a potential predictive marker for survival, we further analyzed its impact on RFS in breast cancer patients stratified by ER status." (PMID 40006048, 2025). "Notably, STC2 mRNA in breast cancer is significantly elevated compared to their corresponding normal tissues (p = 1.44 × 10−2)." (PMID 40006048, 2025). "Regarding other clinical variables contemplated here, STC2 is an estrogen-responsive gene co-expressed with the estrogen receptor in breast cancer, but according to our results, we cannot rule out that the change in the expression of STC2 is linked with the gender of our patients." (PMID 41155293, 2025). "This pattern suggests a widespread but variable overexpression of STC2 in breast cancer cases." (PMID 40006048, 2025). "Given the critical role of STC2 in the stress response, the aim of this work is to evaluate the potential of STC2 as a predictive biomarker of response to chemotherapeutic agents in breast cancer." (PMID 40006048, 2025). "This differential prognostic impact of STC2 expression in breast cancers could be explained by its interaction with ER-mediated signaling pathways." (PMID 40006048, 2025). "Conversely, genes highly expressed in PIPET_LumB, such as STC2, COX6C and DHRS2, may be associated with tumor invasion, metastasis and epithelial–mesenchymal transition in breast cancer." (PMID 38819254, 2024). "To address whether STC2 upregulation is a common phenomenon in different tumour types enduring nutrient insufficiency, we exposed breast cancer cells to Gln-deprivation as well." (PMID 38464261, 2024). "The study identified STC2 as an E2-responsive gene, similar to findings for breast cancer." (PMID 39186548, 2024). "Researches demonstrated that STC2 could impair breast cancer cell growth, migration, and cell viability, which was consistent with our results." (PMID 36998462, 2023). "To summarize, it can be concluded that LncRNA MAFG-AS1 could promote breast cancer cells’ proliferation and metastasis by up-regulating targeted gene STC2." (PMID 35513366, 2022). "Therefore, the value and application of STC2 expression in the prognosis of breast cancers should be further evaluated based on the subtypes and other molecular characteristics." (PMID 35501821, 2022). "Results from our study indicated that knockdown of lncRNA MAFG-AS1 suppressed breast cancer cells migration, invasion and proliferation might by downregulating STC2 in AKT-ERK signaling pathway in breast cancer." (PMID 35513366, 2022). "Therefore, it can be concluded that STC2 can induce DNA damage in the two types of breast cancer cells." (PMID 35607324, 2022). "Our study demonstrated that LncRNA MAFG-AS1 might promote breast cancer cell proliferation and metastasis by regulating the stability of STC2 mRNA." (PMID 35513366, 2022).